RN7SL244P (RNA, 7SL, cytoplasmic 244, pseudogene)
Gene: Miscellaneous RNA gene on chromosome 6 (53,090,961 to 53,091,257, forward strand). Ensembl gene ENSG00000242865.
Homologues: Orthologues: chimpanzee Metazoa_SRP (99% identical), macaque Metazoa_SRP (96% identical). Paralogues in human: RN7SL664P (81% identical), RN7SL1 (80% identical), RN7SL122P (80% identical), RN7SL2 (79% identical), RN7SL804P (79% identical), RN7SL333P (79% identical), RN7SL709P (79% identical), RN7SL714P (79% identical), RN7SL118P (78% identical), RN7SL126P (78% identical), RN7SL218P (78% identical), RN7SL258P (78% identical), and 706 more.